CCL23 (C-C motif chemokine ligand 23)
Diseases named in the same sentence as CCL23 in open-access papers (continued):
Sharing a sentence is not in itself a finding about the gene and the disease.
viral infections (1 paper, 2017). "Given the potent effect of TLR8 agonists in inducing neutrophil-derived CCL23, and its negative regulation by IFNα, data also contribute to extend our knowledge on the complex role of neutrophils to both host defense and disease in response to viral infections." (PMID 28553619, 2017). "Moreover, they also imply that appropriately activated neutrophils may represent major sources of CCL23, even in consideration of the fact that, during bacterial or viral infections, neutrophils often outnumber mononuclear leukocytes by one to two orders of magnitude." (PMID 28553619, 2017).
cancer (30 papers, 2012 to 2025). A tumor composed of atypical neoplastic, often pleomorphic cells that invade other tissues. "CCL23 has been also reported to participate in the recruitment of cancer-related cells and its decrease is associated with shortened patient survival in solid tumors." (PMID 37566023, 2023). "This would also allow us to better understand the threshold level of the cancer–immune set point wherein CCL23 in the ascites shifts the balance to a pro-tumor response." (PMID 41463176, 2025). "CCL23 differed significantly within and between the races with a lower level in AA cancer cases (454.5 vs. 966.6 pg/ml) than healthy controls (740.5 vs. 1263.0 pg/ml)." (PMID 37698493, 2023). "Similar to our data on CCL23, recently, different experimental markers were described as novel prognostic or predictive tools in cancer, however only very few markers reached clinical practice." (PMID 36505756, 2022). "While a role for CCL23 has been described in various cancers, only very limited data on a potential function in the context of BTC exist." (PMID 36505756, 2022). "In support of these observations, we examined the Human Protein Atlas resources for CCL23 protein expression (v20.proteinatlas.org/ENSG00000274736-CCL23/pathology/liver+cancer)." (PMID 34671553, 2021). "First, four out of 16 representative DEGs found in all three subtypes of canine MGTs have strong references in human cancer as biomarkers: CCL23, CXCL10, SFRP2, and FRZB." (PMID 30205506, 2018). "CCL7, CCL23, and IL-32 attract monocytes and macrophages to regulate cancer antigen presentation." (PMID 39235457, 2024). "CCL23, also known as macrophage inflammatory protein-3 (MIP-3), was the only observed chemokine showing race- and cancer-specific differences with significantly high serum levels of CCL23 in CA men than AA, while CCL23 was significantly low in cases with respective races." (PMID 37698493, 2023). "However, CCL23 is a relatively lesser characterized chemokine whose role in cancer suppression remains to be elucidated." (PMID 37698493, 2023). "The chemokine, CCL23 has been found as a cytokine with both, pro- and anti-cancer properties." (PMID 37228491, 2023). "A review states that CCL23 appears to have both anti-cancer and cancer-promoting properties." (PMID 35001801, 2022). "In contrast, there are currently few studies indicating the involvement of CCL23 in cancer." (PMID 35001801, 2022). "There are few studies indicating the involvement of CCL23 in cancer." (PMID 33182504, 2020). "For this reason, it can be assumed that CCL23 increases the proliferation of cancer cells." (PMID 33182504, 2020). "Additionally, the C-C motif chemokine ligand 23 (CCL23), typically secreted by macrophages, may play a role in fueling the growth of cancer cells." (PMID 38229100, 2024). "However, the most important pro-cancer function of CCL23 may be the induction of angiogenesis by activating CCR1 on vascular endothelial cells, a process associated with increased expression and secretion of matrix metalloproteinase (MMP)-2 from these cells." (PMID 33182504, 2020). "CCL23, UM‐SCC1 (human), and SCCVII (HPV−), MEER (HPV+) (murine) H&N cancer cell lines were utilized for in vitro and in vivo studies." (PMID 38686626, 2024). "CCL23 acts by activating its receptor CCR1, which has been found on the surface of both cancer cells and cells of the tumor microenvironment (monocytes, macrophages, dendritic cells, lymphocytes, and endothelial cells)." (PMID 36505756, 2022). "Secretion of CCL23, -24, -25, -26, CXCL12, and -16 was increased in all spheroid cultures upon monocyte addition in a cancer cell line-dependent fashion but was only marginally secreted by control macrophages." (PMID 34451433, 2021). "Pan-cancer analysis of the relationship between OBSCN expression and chemokines revealed a significant negative correlation between OBSCN expression and a variety of chemokines, including CXCL10, CXCL11, CCL11, CCL21, and CCL23." (PMID 40149008, 2025).
cancer (continued). "Most cancer glands (13/20) were negative for CCL23 expression, while other cases showed a weak to moderate level of cytoplasmic positivity." (PMID 37698493, 2023). "Several CC chemokine members, including CCL2 (MCP-1), CCL3 (MIP-1α), CCL5 (RANTES), CCL7 (MCP-3), CCL8 (MCP-2), CCL17 (TARC) CCL 20 (MIP-3α), CCL22 (MDC) and CCL23 (MPIF-1), are produced mainly by tumor infiltrating lymphocytes (TIL) and monocytes, and some of them also by cancer cells." (PMID 24213462, 2012). "CCL18, CCL22, CCL23, and CXCL12 consistently showed a negative correlation across most cancer types, while other anti-inflammatory chemokine genes displayed a more complex, context-dependent relationship, with both positive and negative correlations depending on the specific malignancy." (PMID 40806276, 2025). "CCL15, CCL14, CCL16, CCL23, and CCL27 showed negative relations in more than 10 cancers." (PMID 38655053, 2024).
tumor (27 papers, 2012 to 2025). "In summary, our investigation indicated that the risk model composed of PTGDR, PNOC and CCL23 has potential to predict prognosis and evaluate the tumor immune microenvironment in HPBC patients." (PMID 35665772, 2022). "In this observational cohort study, we measured serum concentrations of CCL23 in a large cohort of BTC patients undergoing tumor resection between 2011 and 2017 and examined the role of CCL23 as a diagnostic and/or prognostic marker in these patients." (PMID 36505756, 2022). "CCL23 increased the diagnostic sensitivity and specificity of established tumor markers including CA19-9 and correlated with patients' age and makers of systemic inflammation." (PMID 36505756, 2022). "The presence of CCL23 may help create a tumor-suppressive environment by recruiting leukocytes to the tumor site and postulate that the loss of CCL23 serves as a driver in the oncogenesis of hepatic tumor cells." (PMID 34671553, 2021). "Patients with low levels of CCL23 tumor mRNA were noted to have significantly better outcomes versus patients with high CCL23 concentrations (HR 1.16 [95% CI 1.0–1.33], p = 0.047)." (PMID 41463176, 2025). "In summary, our study describes a novel interaction between CCL23 and CXCL10 in the tumor microenvironment, which is also associated clinical findings, indicating reduced overall survival with higher CCL23 and lower CXCL10 levels in human ovarian ascites." (PMID 41463176, 2025). "Both CCL22 and CCL23 were immunosuppressive chemokines derived from macrophages, which had a unique role in inhibiting anti-tumor immunity." (PMID 38075694, 2023). "CCL23 induces tumor cell proliferation, stimulates angiogenesis, and acts as a chemoattractant immune effector cells." (PMID 36505756, 2022). "In a next step, we compared serum CCL23 levels between BTC patients of different tumor as well as clinical characteristics." (PMID 36505756, 2022). "In a subgroup of patients, we analyzed levels of circulating CCL23 at the time point of one week after tumor resection to gain further insight into the longitudinal regulation of this chemokine." (PMID 36505756, 2022). "Of these, CD163high TAM are of particular relevance, as they express metastasis‐promoting genes, such as CCL18, CCL23, KITLG and VEGFB17 and are associated with rapid tumour progression and early relapse in HGSC patients." (PMID 34841720, 2021). "The regression model for the observed tumor grade used a combination of only two proteins, CCL23 and WFDC2." (PMID 30451357, 2019). "CCL23, which has both pro-inflammatory and immunomodulatory properties, can also affect the composition of the immune infiltrate within the tumor microenvironment, potentially promoting a more favorable environment for tumor progression." (PMID 40665092, 2025). "In this case, we would hypothesize that CCL23-mediated immunosuppressive effects would exert a more pronounced impact on anti-tumor immunity, particularly due to its known role in promoting the recruitment and accumulation of exhausted T-cells within the TME." (PMID 41463176, 2025). "We found that the IRLPS-high group had decreased expression of CCL23, in line with our previous study that CCL23 could serve as a tumor suppressor through recruiting CD8+ T cell infiltration in liver cancer." (PMID 35277569, 2022). "Interestingly, concentrations of CCL23 remained unchanged after tumor removal." (PMID 36505756, 2022). "Consequently, a decrease in the CCL23 chemokine in hepatic tumors is associated with poor survival of HCC patients and could be a mechanism hepatic tumor cells use to evade the immune system." (PMID 34671553, 2021). "Also, the operational support of Th1 cells may be outweighed due to an anergic or exhausted cytotoxic immune cells ecosystem within the HCC tumor microenvironment due to a low level of CCL23." (PMID 34671553, 2021).
tumor (continued). "To better understand the relationships between CCL23 and CXCL10 expression on patient survival, we performed an in silico assessment of patient outcomes based on the tumor expression levels using datasets hosted in the Cancer Genome Atlas (TCGA) database." (PMID 41463176, 2025). "Hence, we hypothesize that CCL23 chiefly acts as an immune inhibitor and promotes tumor growth." (PMID 35665772, 2022). "This article describes the prospective role of CCL23 in alleviating ER stress and its impact on the HCC tumor microenvironment in promoting antitumor immunity." (PMID 34671553, 2021). "Here, we describe a novel perspective of a CC-chemokine ligand (CCL23) in context with HCC tumor development and its potential in mitigating the ER stress leading to remodeling the HCC tumor microenvironment in favor of enhanced antitumor immunity." (PMID 34671553, 2021). "Given the inverse relationship between CCL23 and CXCL10 in human ovarian ascites samples and reduced survival in patients with low tumor CXCL10 expression, we hypothesized that the activation of CCR1 via CCL23 impairs CXCL10 secretion from myeloid cells." (PMID 41463176, 2025). "High levels of CCL23 were also detected in conditioned media from whole human omentum without tumor and human omentum derived macrophages." (PMID 32963283, 2020). "Like CXCL5, CXCL2 could be an ancestry-related chemokine; however, CCL23 is a novel chemokine that appeared to be independent of ancestry, and its role in tumor suppression warrants further investigation." (PMID 37698493, 2023). "Thus, the CCL23 chemokine likely has a significant potential to alleviate ER stress by rescuing the UPR-sensors and reducing the pro-inflammatory cytokine profile, diminishing the immunosuppressive HCC tumor microenvironment and enhancing antitumor immunity." (PMID 34671553, 2021).
infection (9 papers, 2013 to 2025). The state of being infected such as from the introduction of a foreign agent such as serum, vaccine, antigenic substance or organism. "The other chemokines detected in this study involved in monocyte, T and NK cell recruitment were CCL2, CCL4 and CCL23, which were upregulated in the medium and high dose groups, resulting in an increased number of cells susceptible to infection." (PMID 35854219, 2022). "In conclusion, we identified a group of cytokines, including IL-17C, MMP-10, FGF-23, CCL23, FGF-19 and CXCL5 that are differentially regulated during asymptomatic and mild symptomatic infections and are known to be associated with tissue repair functions." (PMID 35479098, 2022). "In the study, we showed increased circulating concentrations of 47 inflammatory proteins in patients with severe infection compared to healthy controls, with the most robust increase in the circulating concentration observed for TNFSF14, OSM, CCL23, IL-6, and HGF." (PMID 36209073, 2022).
cardiovascular disease (2 papers, 2023 to 2025). "Furthermore, many of the age-associated proteins such as CST5, CCL23, SLAMF1, MMP-1, MCP-1, and CDCP1 have been linked to chronic diseases such as cardiovascular disease and neurocognitive decline in the general population." (PMID 37672793, 2023).
CCL23 also shares sentences with these, for which no sentence is quoted: chronic rhinosinusitis (2 papers); pneumonia (2); rectal cancer (2); vasculitis (2); adenocarcinoma (1); aneurysm (1); atopic dermatitis (1); bacterial infection (1); colitis (1); colon adenocarcinoma (1); Depression (1); diabetes (1); diabetic eye disease (1); Down syndrome (1); endometrium cancers (1); fungal infections (1); gallbladder cancer (1); gastric cancer (1); gastroduodenitis (1); heart failure (1); Hyperglycemia (1); Hyperinsulinemia (1); Hypertension (1); ischemic heart disease (1); kidney failure (1); Klatskin's tumor (1); liver failure (1); macrophage activation syndrome (1); metastatic tumors (1); neurodegenerative disease (1).
A further 10 diseases each share a sentence with CCL23 in 1 paper.